JMJD6 (jumonji domain containing 6, arginine demethylase and lysine hydroxylase)
Diseases named in the same sentence as JMJD6 in open-access papers (continued):
Sharing a sentence is not in itself a finding about the gene and the disease.
tumor (51 papers, 2012 to 2025). "Pathway enrichment analysis showed that the Interferon Type 1 pathway was significantly enriched in JMJD6-deficient tumor cells." (PMID 35359945, 2022). "Intriguingly, SKLB325 treatment and JMJD6 deficiency exerted a remarkable reduction in tumor growth relative to that of the sunitinib‐treated 786‐O cell‐SR or naive 786‐O cell‐SR mice, as quantified by serial bioluminescence signals." (PMID 33634984, 2021). "Results suggested higher tumor expression of JMJD6 in patients with tumor metastasis compared with that of non-metastatic patients (p = 0.017 in LUAD and p = 0.012 in LUSC), indicating that tumor JMJD6 expression is positively associated with metastasis incidence of NSCLC." (PMID 41320721, 2025). "By analyzing tumor immune-related cytokines, they suggested that the combination of IFN and TNF-α cytokines may be the mediators of cell death in JMJD6-deficient tumor cells." (PMID 35359945, 2022). "A Genome-wide CRISPR-CTL screening based on the Mouse Toronto KnockOut (mTKO) CRISPR Library revealed that antigen presentation mediated T cell toxicity was minimal in JMJD6-deficient tumor cells, making JMJD6-deficient tumor cells more suitable for CTL treatment." (PMID 35359945, 2022). "Alternatively, it is possible that JMJD6 could also be mutated in some tumours." (PMID 25951181, 2015). "The boxplots display JMJD6 expression in tumor and normal tissues from other cancer types based on RNA-sequencing data derived from TCGA." (PMID 41320721, 2025). "The expressions of JMJD6 were elevated in both tumor samples (p = 0.002 for LUAD, p = 0.045 for LUSC)." (PMID 41320721, 2025). "Results from Kaplan–Meier survival analysis suggested that NSCLC patients with higher JMJD6 expression had worse prognosis compared to those with low tumor expression of JMJD6." (PMID 41320721, 2025). "In addition, we evaluated whether JMJD6 expression was associated with tumor metastasis status." (PMID 41320721, 2025). "Among the 188 NSCLC patients included in the survival analysis, 172 patients were enrolled with paired tumor tissues and adjacent normal tissues for the comparison of JMJD6 expression." (PMID 41320721, 2025). "We then confirmed the correlation between tumor expression levels of JMJD6 with prognosis in our patient cohort." (PMID 41320721, 2025). "Implantation of each group into immune-deficient mice led to tumor development of MYCN and JMJD6/MYCN groups." (PMID 38488852, 2024). "We found that APA of JMJD6 can result in a functional pivot between acting as an oncogenic protein and acting as a tumor suppressor." (PMID 39349823, 2024). "Depletion of JMJD6 inhibits cancer cell proliferation and impedes tumor growth while overexpression of JMJD6 promotes MYC-mediated tumorigenesis, suggesting that JMJD6 and potentially other 17q genes have oncogenic functions in cellular transformation." (PMID 38488852, 2024). "After treatment with X-ray, the tumor-forming ability of cells in nude mice was markedly diminished in response to JMJD6 depletion, while further ERK2 (MAPK1) overexpression increased the tumor volume and recovered the resistance of cells to radiation." (PMID 37880710, 2023). "The sh-J6 group showed low JMJD6 expression even with tumor-CM stimulation, and the control groups both showed higher JMJD6 expression following tumor-CM stimulation." (PMID 37567973, 2023). "At the end of the experiment, the average tumor weight of Jmjd6+/− mice was significantly decreased." (PMID 37567973, 2023). "This study aims to identify the role of JMJD6 in macrophage polarization and the remodeling of tumor microenvironment composition." (PMID 37567973, 2023). "The tumor growth curves demonstrated a delayed growth of subcutaneous LLC tumors in Jmjd6+/− mice compared with WT mice." (PMID 37567973, 2023). "To validate the results in cancer patients, we assessed the expression levels of JMJD6 with immunofluorescence in tumor stroma of paired human tumors and adjacent normal tissues." (PMID 37567973, 2023).
tumor (continued). "To investigate the underlying mechanisms of JMJD6-modulated macrophage activation, we analyzed the expression level of JMJD6 and M2-polarizing cytokines IL-10 in tumor-CM-activated macrophages." (PMID 37567973, 2023). "The HE staining further suggested that JMJD6 inhibition sensitized mice to PD-1 blockade in terms of tumor formation in lung." (PMID 37567973, 2023). "To examine the role of JMJD6 in THP-1 activation, we detected JMJD6 expression in sh-Scr- or sh-J6- transfected THP-1 cells following tumor-CM stimulation." (PMID 37567973, 2023). "More importantly, the results of Ki-67 staining and TUNEL assay indicated that silencing of JMJD6 inhibited the tumor radioresistance and enhanced cell apoptosis." (PMID 37880710, 2023). "Following stimulation with tumor-CM, BMDMs and PMs of Jmjd6+/− mice displayed significantly lower JMJD6 mRNA levels than WT mice." (PMID 37567973, 2023). "Herein, we review and update the latest role of JMJD6 in tumor development and regulation of innate immune response, providing a new understanding of the JMJC protein family as a potential target for tumor immunotherapy." (PMID 35359945, 2022). "In this article, we have discussed the biological role of JMJD6 and its important role in tumorigenesis, as well as immune response, and found JMJD6 is likely to become an attractive target for novel tumor immunotherapy and prevention." (PMID 35359945, 2022). "The relationship between the abnormal expression of this epigenetic gene in tumors and its immune regulation drives us to further explore the role of JMJD6 in tumorigenesis and tumor immunity." (PMID 35359945, 2022). "In this article, we introduce the structure and biological activities of JMJD6, followed by summarizing its roles in tumorigenesis and tumor development." (PMID 35359945, 2022). "The expression data of the JMJD6 gene in distinct human tumor samples were extracted from the Cancer Genome Atlas (TCGA) database." (PMID 35359945, 2022). "p300/CBP-associated factor-mediated the acetylation of HOXB9 can target JMJD6, leading to decreased cell migration and tumor growth." (PMID 35359945, 2022). "Meanwhile, the classification of different tumor patients and the selection of appropriate JMJD6 inhibitors for individualized treatment will also be the trend of anti-tumor therapy." (PMID 35359945, 2022). "Existing evidence suggests the crucial role of JMJD6 as a tumorigenic factor in several cancers, and the high expression of JMJD6 was found to promote the proliferation and survival of tumor cells and predicted the dismal prognosis of patients." (PMID 35935823, 2022). "JMJD6 functions as an oncogene that contributes to tumor progression by regulation of MAPK, Ras, and ERK signaling pathways." (PMID 35359945, 2022). "ENO1 and JMJD6 were moderately positive while SLC2 was weakly positive in HCC tissues when compared with corresponding expression levels in non-tumor tissues." (PMID 34194464, 2021). "Given its potential role in a number of tumour types, a novel JMJD6 specific inhibitor SKLB325 has recently been developed." (PMID 33925994, 2021). "The immunohistochemical staining and western blot results of subcutaneous tumor tissues of nude mice also indicated that the expression of JMJD6 was significantly increased in the GNA14 overexpression group." (PMID 33500727, 2021). "Simultaneously, we conducted a multivariate Cox analysis using age, pathological stage, and tumor grade and found that JMJD6 still remained one independent predictive marker for the prognosis of RCC (HR = 1.289, 95% CI, 1.136−1.463, P < 0.001)." (PMID 33634984, 2021). "Upregulated JMJD6 expression is related to tumour growth, tumour metastasis and high tumour pathological classification." (PMID 33925994, 2021).
tumor (continued). "JMJD6 expression is correlated with tumor progression, invasiveness and metastasis in several cancer types and is elevated in advanced tumors." (PMID 32927736, 2020). "This analysis suggests a differential role for JMJD6 alternatively spliced isoforms in tumor progression." (PMID 32927736, 2020). "JMJD6 expression is positively correlated with histological grade, age, LN metastasis, tumour size and advanced TNM stage." (PMID 31961032, 2020). "The Fe(II) and 2OG dependent oxygenase JMJD6 is an important factor for embryonic development and it is strongly indicated in controlling tumor progression." (PMID 32927736, 2020). "Significantly high expression of JMJD6 in lung adenocarcinoma was found positively correlated with tumor size and pleural invasion, and led to significantly poor clinical outcomes." (PMID 30002791, 2018). "Many published studies link high expression of JMJD6 with severe pathological tumor grades, increased tumor growth and/or metastasis." (PMID 28360925, 2017). "Based on the percentage of JMJD6-positive tumor cells obtained by immunohistochemical staining, patients were subdivided into low expression group (n = 69) and high expression group (n = 85)." (PMID 28587176, 2017). "We found that, compared to that in control animals, the tumor size was much smaller and the tumor growth rate was significantly slower in mice received Jmjd6-depleted tumor cells." (PMID 29187213, 2017). "A commonly amplified chromosomal region on distal mouse chromosome 11 in tumor samples of three mouse cancer models encompasses the Jmjd6 gene." (PMID 28360925, 2017). "In our experiments, overexpression of JMJD6 in MMTV-Myc tumor cells was able to dramatically increase the number of metastatic nodules in lungs of mice after tail vein injection, as well as invasion and migration of these cells in vitro." (PMID 27081402, 2016). "We, therefore, focused on exploring the cooperation of JMJD6 with c-Myc in cellular transformation, tumor progression, and metastases." (PMID 27081402, 2016). "Further functional analyses of several candidate genes overexpressed in the mouse 11q locus revealed that the epigenetic modifier JMJD6 is able to inhibit Myc-induced apoptosis, which is critical for tumor progression." (PMID 27081402, 2016). "JMJD6 overexpression in MMTV-Myc cell lines increases tumor burden, induces EMT, and greatly enhances tumor metastasis." (PMID 27081402, 2016). "We first knocked down JMJD6 in Myc83 cells with elevated JMJD6 expression using two different shRNAs and found a significant delay in tumor formation compared to control cells when injected into mouse mammary fat pad." (PMID 27081402, 2016). "Using cell lines stably overexpressing or knocked down for JMJD6, we evaluated its role on cell proliferation, cell migration, colony formation and mice tumour xenografts." (PMID 25951181, 2015). "JMJD6 silencing in breast tumoural cells promotes certain characteristics of tumourigenesis including proliferation, migration in vitro, and tumour growth in vivo." (PMID 25951181, 2015). "Altogether, these results clearly establish that JMJD6 possesses anti-tumoural properties as measured by its negative effect on cell proliferation, migration, colony formation and tumour engraftment." (PMID 25951181, 2015). "JMJD6 is a novel biomarker of tumor aggressiveness with functional implications in breast cancer growth and migration." (PMID 22621393, 2012). "Consistent with its potential as a marker of breast cancer aggressiveness, JMJD6 was expressed at highest levels in ER-, basal, claudin-low, HER2-enriched, and Luminal B tumor subtypes, which are known to be clinically associated with poor patient outcomes." (PMID 22621393, 2012).
tumor (continued). "Notably, increased JMJD6 expression was observed in tumor samples in contrast to epithelial cells in the adjacent and normal samples." (PMID 41320721, 2025). "JMJD6 OE or PFTα treatment mitigated the anti-tumor effects of si CCNB2 both in vitro and in vivo." (PMID 38166895, 2024). "To examine whether JMJD6 amplification is limited to specific tumor types, we explored genomic data from different cancers using the cBioportal program." (PMID 38488852, 2024). "Likewise, in the B16F10 pulmonary metastasis model, the Jmjd6 knockdown impaired tumor growth as demonstrated by reduced number of lung metastasis and lung weights." (PMID 37567973, 2023). "In addition, based on datasets of GEPIA2, we found that JMJD6 was highly expressed in ESCA compared with non-tumor tissues (p < 0.05)." (PMID 37488513, 2023). "Notably, western blot results showed that tumor-CM effectively elevated JMJD6 expression level, which was also found to be increased in TC-Mφ cells compared with M0-like THP-1 cells." (PMID 37567973, 2023). "Mechanistically, GNA14 likely controls the retinoblastoma pathway by inducing Notch1 cleavage to stop tumor growth, and it may also prevent tumor cell migration by suppressing the expression of Jumonji domain-containing 6 (JMJD6)." (PMID 38304027, 2023). "Additionally, JMJD6 has been studied in relation to sunitinib sensibility, results showing that JMJD6 inhibitors act synergistically with sunitinib, increasing tumor sensitivity to it." (PMID 37228649, 2023). "In addition to the tumor expression of JMJD6, recent studies suggested that the correlation of JMJD6 with tumor prognosis was not only based on tumor cell-intrinsic mechanisms, but also the molding the TME." (PMID 37567973, 2023). "Tumors of Jmjd6+/− mice displayed decreased CD31 and Ki67 positivity compared with WT mice, suggesting Jmjd6 deficiency in macrophages resulted in decreased intratumoral vascular density and tumor cell proliferation." (PMID 37567973, 2023). "Moreover, in the tumor tissues of mice after JMJD6 silencing, the expression of HOTAIR was restricted, while further overexpression of ERK2 (MAPK1) did not affect the expression of HOTAIR." (PMID 37880710, 2023). "Notably, although tumor cells constitute the majority of tumor bulks, the average JMJD6 expression level in tumor cells was significantly lower compared with tumor-infiltrating immune cells." (PMID 37567973, 2023). "Moreover, JMJD6 knockdown overcame the tumor resistance to anti-PD-1 treatment, making TAMs-targeted therapy a potential combination partner for ICB therapies." (PMID 37567973, 2023). "Accordingly, blocking the JMJD6-STAT3 axis by JMJD6-knockdown impaired tumor growth in vivo." (PMID 37567973, 2023). "Based on the regulatory role of JMJD6 in immunosuppression, we investigated whether targeting JMJD6 in macrophages had a synergistic effect with PD-1 blockade in inhibiting tumor growth and metastasis." (PMID 37567973, 2023). "Interestingly, we found that CLO Lipo reduced the difference in tumor growth between WT mice and Jmjd6+/− mice." (PMID 37567973, 2023). "Univariate analysis showed that JMJD6 expression (HR = 2.282 [1.509–3.451], p < 0.001), lymphatic metastasis (HR = 1.806 [1.204–2.710], p = 0.004), and tumor-node-metastasis (TNM) stage (HR = 1.731 [1.150–2.605], p = 0.008) were associated with ESCC patients’ survival." (PMID 37488513, 2023). "Further, the authors explored the role of JMJD6 interference in T cell killing of tumor cells." (PMID 35359945, 2022). "The seemingly contradictory characteristics of JMJD6 may be owing to types of tumor tissue or cell lines and H2A serine phosphorylation site, yet further investigations are still needed." (PMID 35359945, 2022).
tumor (continued). "However, JMJD6 expression was markedly diminished in several tumor types, i.e., thyroid cancer (THCA) and renal chromophobia (KICH), and its low expression resulted in poor DFS in THCA." (PMID 35359945, 2022). "Recently, in a co-cultured experiment, JMJD6 deficiency enhanced the sensitivity of a variety of tumor cells to T cell killing, implying JMJD6 might be a CTL-evasion gene in tumor immunity." (PMID 35359945, 2022). "In other words, JMJD6 may maintain the balance of tumor microenvironment and tumor cell growth by selectively regulating various immune cells and immunomodulatory genes that have pro-cancer or anti-cancer effects." (PMID 35359945, 2022). "Furthermore, the expression of JMJD6 is mutually exclusive of the tumor immune checkpoints, such as VEGFA, ARG1, EDNRB, IL13, IL12A, CD274 and KIR2DL3 in the majority of cancers, like THYM and HNSC, etc." (PMID 35359945, 2022). "In RCC, JMJD6 transcription activation may contribute to tumor development, via inducing p300-mediated H3K27ac." (PMID 35359945, 2022). "However, JMJD6 was found to be positively correlated with regulatory T cells (Tregs) that inhibit anti-tumor immunity and M2 macrophages that promote tumor growth." (PMID 35359945, 2022). "Therefore, studying the key roles and mechanisms of JMJD6 in tumor treatment will provide a sufficient experimental and theoretical basis for future clinical applications." (PMID 35359945, 2022). "Importantly, we highlight the potential functions of JMJD6 in the regulation of tumor immune response, as well as the development of JMJD6 targeted small-molecule inhibitors for cancer therapy." (PMID 35359945, 2022). "It is speculated that JMJD6 may be a novel biomarker and potential target for tumor prediction and treatment." (PMID 35359945, 2022). "GNA14 regulated the RB pathway by promoting Notch1 cleavage to inhibit tumor proliferation, and might inhibit tumor metastasis by inhibiting the expression of JMJD6." (PMID 33500727, 2021). "Increased expression of JMJD6 has frequently been detected in many different neoplasms." (PMID 33684176, 2021). "Finally, we conducted the pan‐cancer analysis using the expression data from 33 tumors and found that JMJD6 was highly expressed in RCC patients compared with most of other tumor types." (PMID 33634984, 2021). "Moreover, based on the analysis of the TCGA‐KIRC cohort, high expression of JMJD6 correlated positively with advanced TM stages, pathological stages, and tumor grades (P < 0.01)." (PMID 33634984, 2021). "In addition, to determine the roles of JMJD6 in vivo, we performed tumor xenograft studies and observed that knocking out JMJD6 significantly suppressed tumor growth, as quantified by tumor size, compared with tumors derived from control group." (PMID 33634984, 2021). "Expression of JMJD6 in ER+ tumours is slightly but significantly lower than ER− tumours." (PMID 31961032, 2020). "JMJD6 is highly expressed in more aggressive and advanced tumours." (PMID 31961032, 2020). "JMJD6 is significantly correlated with tumour grade and TNM stage." (PMID 31961032, 2020). "Moreover, JMJD6 overexpression can induce epithelial‐mesenchymal transformation and greatly enhance tumour growth and invasion." (PMID 31961032, 2020).